CSF1R (colony stimulating factor 1 receptor)
Diseases named in the same sentence as CSF1R in open-access papers (continued):
Sharing a sentence is not in itself a finding about the gene and the disease.
frontotemporal dementia (6 papers, 2018 to 2026). Frontotemporal dementia (FTD) comprises a group of neurodegenerative disorders, characterized by progressive changes in behavior, executive dysfunction and language impairment, as a result of degeneration of the medial prefrontal and frontoinsular cortices. "Pathogenic variants in CSF1R gene have been increasingly reported in subjects with EOD, mostly clinically mimicking behavioral variant of frontotemporal dementia (bvFTD)." (PMID 41634195, 2026).
gastrointestinal stromal tumor (6 papers, 2010 to 2022). "Sunitinib is an orally bioavailable multityrosine kinase inhibitor that blocks VEGFR1-3, Flt-3, PDGFR-α, PDGFR-β, c-Kit, CSF-1R, and RET with proven antitumor activity in renal cell carcinoma and imatinib-resistant or -intolerant gastrointestinal stromal tumor (GIST)." (PMID 21961001, 2012). "Furthermore we evaluated the gene expression of KIT as well as the alternative RTK FLT3, CSF1-R, PDGFRB, AXL and MET in mutated and non-mutated gastrointestinal stromal tumors by qPCR using the identified reference genes." (PMID 21171987, 2010).
ischemic stroke (6 papers, 2020 to 2024). A stroke disorder caused by obstruction of blood flow to the brain, due to thrombotic (local blood clot formation) or embolic (due to a blood clot or other material traveling from another site) event. "Depletion of microglia by CSF1R inhibitor exacerbated ischemic infarction and neurological deficits following ischemic stroke." (PMID 32522286, 2020). "The inhibition of CSF1R signaling has a neuroprotective role in several diseases, including ischemic stroke." (PMID 33192177, 2020). "However, the optimized integration of TP and Ki20227 showed that TP and Ki20227 can inhibit the CSF1R pathway to protect neurons in ischemic stroke." (PMID 33192177, 2020). "Interestingly, repopulated microglia after CSF1R inhibition resembled a similar transcriptional profile following ischemic stroke and could largely attenuate the detrimental effects of microglial depletion after MCAO." (PMID 38151703, 2024). "However, microglial depletion by CSF1R inhibitor resulted in dramatically increased the number of neutrophils and augmented the astrocytic production of inflammatory mediators in brain tissues, which eventually exacerbated neurological deficits and brain infarction after ischemic stroke." (PMID 32522286, 2020). "Therefore, inhibition of CSF1R in the microglia may have a negative clinical effect following ischemic stroke." (PMID 33177990, 2020).
lupus (6 papers, 2019 to 2025). "Glial glutamate transporter activities recorded from astrocytes in the spinal dorsal horn obtained from lupus mice were enhanced upon bath-perfusion of the CSF-1R inhibitor (GW2580)." (PMID 38612414, 2024). "Further, the treatment with CSF-1R inhibitor was confirmed to significantly ameliorate renal injury in murine lupus." (PMID 37876929, 2023). "The role of CSF-1 in the genesis of thermal hypersensitivity in lupus mice was evaluated by measuring the latencies of hind paw withdrawal responses to radiant heat stimuli before and after the intrathecal injection of a CSF-1R inhibitor (GW2580)." (PMID 38612414, 2024). "Conversely, in spinal slices from lupus mice, following confirmation of the enhanced glial glutamate transporter activity by the CSF-1R inhibitor, the additional inhibition of IL-1β through bath perfusion of IL-1ra did not produce a significant alteration in glial transporter activity." (PMID 38612414, 2024). "In addition, depletion of microglia with PLX5622, a selective inhibitor of colony-stimulating factor 1 receptor (CSF1R), maintained dendritic integrity and alleviated depressive behavior in MRL/lpr mice, suggesting that microglia-mediated engulfment contributes to synapse loss in lupus mice." (PMID 40048256, 2025). "Whereas a number of studies have claimed that both CSF-1 and -2 drive M2 skewing of Mφ in mice with AKI, it was controversially found that IL-34, another ligand for CSF-1R, does not polarize Mφ in murine AKI and lupus model, indicating that CSF-1R signaling is dispensable in M2 Mφ polarization." (PMID 31447703, 2019).
Nasu-Hakola disease (6 papers, 2017 to 2022). "Deficiency in TREM2 leads to Nasu-Hakola disease and patients with partial loss-of-function mutations in CSF1R suffer from hereditary diffuse leukoencephalopathy with spheroids (see reviews)." (PMID 29448957, 2018). "In patients diagnosed with AD we found three C9orf72 expansions, nine DVs in MAPT, five in CSF1R, two in GRN, three in PRNP and one each in SQSTM1, TARDBP and VCP, as well as a homozygous TREM2 DV normally associated with Nasu-Hakola disease." (PMID 30279455, 2020).
non-small cell lung carcinoma (6 papers, 2021 to 2025). A group of at least three distinct histological types of lung cancer, including non-small cell squamous cell carcinoma, adenocarcinoma, and large cell carcinoma. "Only one genome-wide association study using a Korean non-small cell lung cancer cohort reported the impact of CSF1R c.1085A>G variant (rs10079250) on clinical outcome." (PMID 34830445, 2021). "Using a non-small cell lung cancer-bearing mouse model, the tumor was irradiated alone or in combination with the CSF-1R inhibitor GW2580 (selective blockade of CSF-1R self-phosphorylation and activation) for 20 Gy." (PMID 40007537, 2025).
chronic GVHD (5 papers, 2021 to 2025). "In 2024, the FDA approved axatilimab, a CSF-1R inhibitor that targets monocyte-derived macrophages in fibrotic chronic GVHD, and remestemcel-L, an allogeneic mesenchymal stromal cell therapy, for pediatric steroid-refractory acute GVHD." (PMID 40722603, 2025). "CSF1R can be used to treat chronic graft-versus-host disease and tumors." (PMID 39780291, 2025). "Indeed, promising clinical trials of anti-CSF1R in chronic graft versus host disease have been based on a repeated intermittent treatment [123•]." (PMID 36197652, 2022).
classical Hodgkin lymphoma (5 papers, 2015 to 2024). "In addition, CSF1R targeting small molecules, including ARRY-382, PLX7486, BLZ945, and JNJ-40346527, which target the intracellular tyrosine kinase of CSF1R, are in completed or ongoing studies in solid tumors and classical Hodgkin lymphoma." (PMID 33968014, 2021). "Although CSF-1R expression is generally thought to be restricted to myeloid lineage cells, recent studies convincingly demonstrated its aberrant expression on non-myeloid lineage cells, including malignant B cells and classic Hodgkin lymphoma." (PMID 35326399, 2022).
depression (5 papers, 2020 to 2025). "In a mouse model, the inhibition of CSF1R signaling reduced the brain expression of pro-inflammatory cytokines and attenuated depression performance, indicating that CSF1R is a potential target for treating NPSLE in the future." (PMID 36078885, 2022).
endometriosis (5 papers, 2019 to 2024). The growth of functional endometrial tissue in anatomic sites outside the uterine body. "In general, targeting the IL-34/CSF1R/JAK3/STAT6 pathway with a STAT6 inhibitor was an effective means of treating endometriosis in rats." (PMID 31727934, 2019). "In summary, autocrine production of IL-34, mediated by STAT6, promoted the development of endometriosis in vitro and in vivo through the CSF1R/JAK3/STAT6 pathway." (PMID 31727934, 2019). "Additionally, treatment with pexidartinib decreases inflammatory signaling and cell survival in endometriosis by suppressing macrophage-colony stimulating factor 1 receptor and stem cell growth factor receptor KIT." (PMID 38698459, 2024). "We also found that macrophages coexpressing CSF-1R and CD169 were more abundant in the PF of endometriosis patients than in that of controls." (PMID 35260161, 2022). "From the data analysis, we found that in the PF of endometriosis patients, the coexpression of DC-SIGN and CD169 at macrophages was greater than that in the control group, and the coexpression of CSF-1R and CD169 by macrophages was greater than that in the control group." (PMID 35260161, 2022). "Further, an IL-34 neutralizing antibody could attenuate CSF1R/JAK3/STAT6 activation and down-regulate VEGF, MMP-2 and MMP-9, eventually leading to suppression of the development of endometriosis in vitro." (PMID 31727934, 2019). "Although the protein expression level of CSF-1R in the ectopic lesions of endometriosis patients was not different from that in the eutopic endometrium of endometriosis patients and the normal endometrium, the gene expression level of CSF-1 was significantly higher in these lesions." (PMID 35260161, 2022).
Hydrocephalus (5 papers, 2019 to 2024). Hydrocephalus is an active distension of the ventricular system of the brain resulting from inadequate passage of CSF from its point of production within the cerebral ventricles to its point of absorption into the systemic circulation. "Mutations in Csf1r, resulting in reduced macrophages, consistently lead to hydrocephalus in Csf1r−/− mice, 1‐year‐old Csf1r+/− mice and humans with biallelic CSF1R mutations, indicating a protective role of cpMs in fetal and childhood hydrocephalus." (PMID 39496482, 2024). "Homozygous mutation (Csf1rE631K/E631K) phenocopied the Csf1r knockout, with prenatal mortality or severe postnatal growth retardation and hydrocephalus." (PMID 35333324, 2022). "Here, we report a new HDLS family with a novel CSF1R mutation, in which the prominent clinical characteristics are associated with hydrocephalus." (PMID 31093799, 2019). "The mechanisms underlying hydrocephalus in both mouse and rat Csf1rko and bi-allelic human CSF1R mutations are unknown but likely unrelated to microglial deficiency." (PMID 34081701, 2021). "We report familial cases of a novel CSF1R mutation causing HDLS similar to hydrocephalus." (PMID 31093799, 2019). "Recently, the role of microglia in animal models of adult brain disorders was examined using cell type-specific ablation by colony-stimulating factor-1 receptor (CSF1R) inhibitor, however, little information exists regarding the role of microglia in neonatal brain disorders such as hydrocephalus." (PMID 37296418, 2023).
inflammatory bowel disease (5 papers, 2013 to 2023). A spectrum of small and large bowel inflammatory diseases of unknown etiology. "In addition, using an established model for inflammatory bowel disease, we show that heterozygous loss of the Csf1r gene is protective in male mice." (PMID 23451116, 2013). "Taken together, our findings suggest that inhibition of CSF-1/CSF-1R signaling by JNJ-40346527 may be effective in managing inflammatory bowel disease." (PMID 31710624, 2019). "Differential intestinal expression of the macrophage growth factors colony stimulating factor-1 (CSF-1), interleukin (IL)-34, and their shared CSF-1 receptor (CSF-1R) in inflammatory bowel disease (IBD) has been shown." (PMID 27898738, 2016). "PTPRZ1 involvement has been linked to various inflammatory diseases such as inflammatory bowel disease (IBD) and lupus nephritis, where PTPRZ1 expression was found to correlate with IL-34, CSF1, and CSF-1R expression." (PMID 36530919, 2022).
injury (5 papers, 2019 to 2024). Damage inflicted on the body as the direct or indirect result of an external force, with or without disruption of structural continuity. "Inhibitors of microglia through the colony-stimulating factor 1 receptor (CSF-1R), such as PLX5622 and neutralizing colony-stimulating factor 1 (CSF-1) antibody, also reduce microglial activation and proliferation in the spinal dorsal horn after nerve injury and alter pain responses." (PMID 35976535, 2023). "Recent data indicated that microglial repopulation following experimental depletion using pharmacological colony-stimulating factor 1 receptor (CSF1R) inhibition could effectively resolve inflammation and promote disease recovery after brain injury, without any apparent adverse effects." (PMID 32957621, 2020).
medulloblastoma (5 papers, 2019 to 2023). A malignant, invasive embryonal neoplasm arising from the cerebellum. "At present, animal trials have showed an anti-tumor effect of STAT3 inhibitors and CSF1R inhibitors in medulloblastoma." (PMID 35860588, 2022). "Additionally, we have recently shown that CSF1R has anti-tumoral effects, and targeting it results in accelerated tumor growth in the most common malignant pediatric brain tumor, medulloblastoma." (PMID 33766119, 2021). "In addition, it was recently demonstrated that in the most common malignant pediatric brain tumor, medulloblastoma, CSF1R has an anti-tumoral affect, and targeting it resulted in accelerated tumor growth." (PMID 33766119, 2021). "Hence, the treatment of mice harboring SMO-mutated SHH-activated medulloblastomas with PLX5622, an inhibitor of the colony-stimulating factor 1 receptor (CSF1R), resulted in a reduced proportion of TAMs in the tumor microenvironment, shrinkage in tumor sizes, and prolonged survival of the mice." (PMID 37568705, 2023). "Similar to this study, we did not observe TAM depletion in medulloblastoma tumours after CSF1R inhibition." (PMID 31160587, 2019). "Tumor-associated macrophages/microglia (TAMs) can accelerate the development of tumor in the medulloblastoma sonic hedgehog subgroup (SHH-MB), As TAMs generally rely on the colony-stimulating factor 1 receptor (CSF1R), the inhibition of CSF1R may have curative promise in SHH-MB patients." (PMID 35574421, 2022).
periodontitis (5 papers, 2017 to 2026). An acute or chronic inflammatory process that affects the tissues that surround and support the teeth. "In this study, we initially assessed the association between macrophage senescence, glycolysis, and CSF-1R in periodontitis using animal experiments." (PMID 40460514, 2025). "PLX3397 alleviates macrophage senescence by modulating glycolysis, uncovering a mechanistic link between CSF-1R signalling, immune metabolism, and senescence in periodontitis." (PMID 40460514, 2025). "Bioinformatics analysis of the GSE10334 dataset demonstrated that CSF-1R is significantly upregulated in periodontitis compared to controls." (PMID 40460514, 2025). "The interplay between CSF-1R signalling and osteoclast activity in periodontitis represents a critical area for future research." (PMID 40460514, 2025). "PLX3397, known for inhibiting CSF-1R, has demonstrated therapeutic potential in attenuating periodontitis progression." (PMID 40460514, 2025). "This study provides evidence that CSF-1R inhibition alleviates macrophage senescence by suppressing glycolysis in the context of periodontitis." (PMID 40460514, 2025). "The gingival tissues of mice with periodontitis showed elevated senescent macrophages, which correlated with higher CSF-1R expression and glycolytic activity." (PMID 40460514, 2025). "Our research that mice with periodontitis exhibited higher expression of CSF-1R+ p16+ macrophages in periodontal tissues, and there was an increase in CSF-1R expression in RAW264.7 cells when stimulated by Pg-LPS." (PMID 40460514, 2025). "Clinical studies have established the involvement of CSF-1R in the inflammatory progression of various types of periodontitis, including chronic periodontitis, aggressive periodontitis, and diabetic periodontitis." (PMID 40460514, 2025). "According to the box plot, the periodontitis group (PDs) exhibits increased CSF-1R expression relative to the normal control group (N), highlighting its potential role in periodontal inflammation." (PMID 40460514, 2025). "To investigate the relationship between macrophage senescence and CSF-1R, we established a murine periodontitis model via molar ligation." (PMID 40460514, 2025). "Elevated expression of CSF-1R in macrophages mediates the release of inflammatory factors and drives inflammatory alveolar bone resorption, contributing to the pathological progression of periodontitis." (PMID 40460514, 2025). "Additionally, in LPS-induced experimental periodontitis, CSF-1R blockade has demonstrated an osteoprotective effect by reducing osteoclast formation and alveolar bone resorption." (PMID 40460514, 2025). "In periodontitis patients, MMP12 production and other inflammatory mediators were attenuated in response to the blocking of CSF-1 receptor (CSF-1R) in the inflamed gingiva and circulating monocytes." (PMID 36902078, 2023). "Notably, the down-regulation of miR-1260b, miR-1224-5p, miR-3156-5p and miR-4286 may contribute to the progression of periodontitis by promoting the expression of NEDD9, P2RX5 and CSF1R." (PMID 41992052, 2026).
skin cancer (5 papers, 2017 to 2023). "Our detection of CSF1R and CSF1/IL34 interaction between cancer and immune infiltrating cells at the epidermal layers was consistent to the biological context of the skin cancer." (PMID 35967449, 2022).
T cell lymphoma (5 papers, 2015 to 2024). "This FDA-approved CSF-1R inhibitor also interferes with the growth and survival of T cell lymphoma cells by acting on both tumoral and microenvironmental cell pools." (PMID 38254773, 2024). "On the contrary, in T-cell lymphoma cells, CSF-1R activation led to AKT phosphorylation in a PI3K-dependent manner." (PMID 38254773, 2024). "CSF1R has also been found to boost the viability of T-cell lymphoma." (PMID 35340229, 2022). "This hypothesis is further supported by our unbiased, high-throughput screen demonstrating that, at least within a T-cell lymphoma context, LAMs are relatively “resistant” to selective CSF1R antagonists, and is compatible with similar findings in other model systems." (PMID 36970721, 2022).
Adult onset (4 papers, 2015 to 2026). Onset of disease manifestations in adulthood, defined here as at the age of 16 years or later. "There are obvious parallels with another adult-onset microgliopathy, Nasu–Hakola disease, which is associated with mutations in TREM2 or the adaptor, TYROBP, which lie downstream of CSF1R in regulation of microglial survival." (PMID 35333324, 2022).
anemia (4 papers, 2018 to 2025). A reduction in the number of red blood cells, the amount of hemoglobin, and/or the volume of packed red blood cells. "DLTs in phase I trials of Aurora kinase inhibitors were primarily hematological events, particularly neutropenia, and DLTs for CSF-1R inhibitor included INR increase, lymphopenia, AST increase, anemia, neutropenia, and syncope." (PMID 30642372, 2019). "Nevertheless, the overall burden of disease was minimal; both fetal and adult Csf1r-MCM+;E76K cohorts had delayed onset of anemia, minimal monocytosis, and lacked leukocytosis." (PMID 29774106, 2018).